PLCD4 (phospholipase C delta 4)
Description:
Hydrolyzes the phosphatidylinositol 4,5-bisphosphate (PIP2) to generate 2 second messenger molecules diacylglycerol (DAG) and inositol 1,4,5-trisphosphate (IP3). DAG mediates the activation of protein kinase C (PKC), while IP3 releases Ca(2+) from intracellular stores. Required for acrosome reaction in sperm during fertilization, probably by acting as an important enzyme for intracellular Ca(2+) mobilization in the zona pellucida-induced acrosome reaction. May play a role in cell growth. Modulates the liver regeneration in cooperation with nuclear PKC. Overexpression up-regulates the Erk signaling pathway and proliferation. [Isoform 2]: Acts as a non-receptor guanine nucleotide exchange factor which binds to and activates guanine nucleotide-binding protein (G protein) alpha subunit GNAI3.
Tractability: Antibody: its Gene Ontology location is reachable by antibodies, with high confidence; UniProt places it where antibodies can reach, with medium confidence.
Gene: Protein-coding gene on chromosome 2 (218,607,855 to 218,637,186, forward strand). Ensembl gene ENSG00000115556.
Subcellular location: Cell membrane; Nucleus; Cytoplasm; Endoplasmic reticulum
Subcellular location (Human Protein Atlas): Cytosol; Endoplasmic reticulum; Plasma membrane
Pathways (Reactome):
Metabolism: Synthesis of IP3 and IP4 in the cytosol
Gene Ontology:
Molecular function: phosphatidylinositol phospholipase C activity; phosphatidylinositol-4,5-bisphosphate phospholipase C activity; protein binding; calcium ion binding; phosphoric diester hydrolase activity
Biological process: intracellular signal transduction; lipid metabolic process; signal transduction
Cellular component: cytoplasm; cytoplasmic side of plasma membrane; cytosol; endoplasmic reticulum membrane; plasma membrane; endoplasmic reticulum; nucleus
Genetic constraint (gnomAD): Loss-of-function variants: 63 observed, 96.82 expected, observed/expected ratio (o/e) 0.65, 90% interval 0.53 to 0.8. The synonymous counts are far from expectation, so gnomAD's model fits this gene poorly and the ratio says little. Missense variants: 830 observed, 997.34 expected, observed/expected ratio (o/e) 0.83, 90% interval 0.79 to 0.88. Synonymous variants: 294 observed, 372.71 expected, observed/expected ratio (o/e) 0.79, 90% interval 0.72 to 0.87.
Homologues: Orthologues: chimpanzee PLCD4 (99% identical), macaque PLCD4 (98% identical), pig PLCD4 (87% identical), dog PLCD4 (85% identical), rabbit PLCD4 (84% identical), guinea pig PLCD4 (82% identical), mouse Plcd4 (75% identical), rat Plcd4 (74% identical), tropical clawed frog plcd4 (60% identical), zebrafish plcd4a (57% identical), zebrafish plcd4b (53% identical), Caenorhabditis elegans plc-3 (33% identical), and 4 more. Paralogues in human: PLCD3 (48% identical), PLCD1 (46% identical), PLCH2 (42% identical), PLCH1 (40% identical), PLCL2 (39% identical), PLCL1 (38% identical), PLCZ1 (35% identical), PLCE1 (33% identical), PLCB3 (33% identical), PLCB1 (33% identical), PLCB4 (33% identical), PLCB2 (33% identical), and 2 more.
Diseases named in the same sentence as PLCD4 in open-access papers:
PLCD4 is named in the same sentence as 23 diseases in open-access papers, as found by Europe PMC text mining. Sharing a sentence is not in itself a finding about the gene and the disease. The quoted sentences say what the papers report.
breast carcinoma (2 papers, 2012 to 2014). "The lack of PLCD4 activity in genetically ablated mice causes disturbances of liver regeneration and interferes with the acrosome reaction in spermatozoa, while over-expression of Plcd4 in a breast cancer cell line induces anchorage-independent growth." (PMID 22723964, 2012).
pancreatic cancer (2 papers, 2020 to 2022). "First, the sample size used for the survival analysis was not large enough, which led to many false‐negative results regarding PLCD1 and PLCD4, especially since PLCD1 has been shown to inhibit pancreatic cancer cell growth in other studies." (PMID 31808619, 2020).
Arrhythmia (1 paper, 2015). Any cardiac rhythm other than the normal sinus rhythm. "Moreover, calcium handling and contractile function genes (SLN, ACTC1, PLCD4, PLCZ), potential arrhythmia-related genes (MYO5B, KCNA5), and cytoskeleton and cellular organization-related genes (XIRP2, COL8A1, KCNA6) were among the most deregulated genes in rTOF ventricles." (PMID 26252659, 2015).
cardiomyopathy (1 paper, 2015). A disease of the heart muscle or myocardium proper. "Interestingly, a pathway analysis based on grouping the differentially expressed genes uncovered that cardiomyopathy-related pathways and phosphatidic acid (PA) pathways (Dgki, Dgkz, Plcd4) were up-regulated." (PMID 25860951, 2015).
Ewing sarcoma (1 paper, 2024). A small round cell tumor that lacks morphologic, immunohistochemical, and electron microscopic evidence of neuroectodermal differentiation. "We investigated the expression of PLCδ4 in eleven human sarcoma cell lines: osteosarcoma (SaOS-2, U2OS, Hos, MG63), Ewing sarcoma (A673), liposarcoma (T778 and SW872), and RMS (RD, A204, Hs729, and SJCRH30)." (PMID 39334946, 2024).
male infertility (1 paper, 2022). The inability of the male to effect fertilization of an ovum after a specified period of unprotected intercourse. "It has been reported that inositol trisphosphate receptor phospholipase C (PLC) and PLCδ4 were present in acrosomes, and that PLCδ4 gene-deficient mice were affected by male infertility." (PMID 36012324, 2022).
meningioma (1 paper, 2023). A generally slow growing tumor attached to the dura mater. "Interestingly, seven of the meningioma-associated antigens were shared between all WHO grades (NMA2, TBX15/18, XXLT1, SLC25A44, RHOD, CREBL2, and PLCD4)." (PMID 37368072, 2023).
nephrotic syndrome (1 paper, 2022). A collection of symptoms that include severe edema, proteinuria, and hypoalbuminemia; it is indicative of renal dysfunction. "The phospholipase C gene encoded by PLCD4 is crucial for the functional development of the glomeruli and the development of nephrotic syndrome." (PMID 35630098, 2022).
neuroblastoma (1 paper, 2022). Neuroblastoma (NB) is the most common solid, extracranial childhood tumor. "The screening results of the RF classifier showed that EPS8L1, PLCD4, CHD5, NTRK1, and SLC22A4 were the most characteristic DEG genes among high-risk neuroblastoma-related genes." (PMID 35911385, 2022). "The screening results of RF showed that EPS8L1, PLCD4, CHD5, NTRK1, and SLC22A4 were the feature differentially expressed genes (DEGs) of high-risk neuroblastoma." (PMID 35911385, 2022).
Obesity (1 paper, 2020). Accumulation of substantial excess body fat. "Based on the obtained results, the ZSCAN32, PLCD4, HOXC13, and ADCY9 from obesity predicted genes, as well as LIMA1, and SLC22A23 from CRC predicted genes were significantly related to CRC survival rate." (PMID 33073494, 2020).
pancreatic ductal carcinoma (1 paper, 2022). "By analysing PanCancer genomic data, we then asked whether PLCD4, PLCB4 and PLD3 levels correlate to the pathogenesis of human pancreatic ductal carcinoma." (PMID 35255936, 2022).
preeclampsia (1 paper, 2024). Preeclampsia is a hypertensive disorder of pregnancy that is characterized by new-onset hypertension with proteinuria presenting after 20 weeks of gestation, and depending on mild or severe forms may initially present with severe headache, visual disturbances, and hyperreflexia. "Proportionately, proteomic PLCD4 (p.L696P) analyses of human placental tissues have shown that ANXA4 expression is downregulated in preeclampsia (PE) placentas and PE placenta-derived extravillous cytotrophoblasts compared with the expression in normal placentas." (PMID 39399103, 2024).
sarcoma (1 paper, 2024). A usually aggressive malignant neoplasm of the soft tissue or bone. "Based on previous observations indicating that PLCδ4 is mainly nuclear in mesenchymal stromal stem cells (hASCs), in this investigation, the expression of PLCδ4 was examined in several sarcoma cell lines." (PMID 39334946, 2024). "When comparisons were made, we found that PLCδ4 is expressed more intensely in the A204 RMS cell line, while it is only slightly detected in the RD RMS cell line and almost completely absent in the remaining sarcoma cells." (PMID 39334946, 2024).
squamous cell carcinoma (1 paper, 2016). A carcinoma arising from squamous epithelial cells. "Potential tumor suppressor genes, also found in other squamous cell carcinomas, have been discovered in the lost regions 2q33-q37.3 (PLCD4), 3p26.3-q11.1 (RBMS3, PLCD1, and CACNA2D3) and 11q12.2-q25 (CPT1A, CCND1, FGF4/FGF3, and PPP2R1B)." (PMID 26901676, 2016).
cancer (2 papers, 2022 to 2024). A tumor composed of atypical neoplastic, often pleomorphic cells that invade other tissues. "In our experimental model of ERMS RMS using the RD cell line, PLCδ4 appears to exert an opposing effect, which is likely related to the form of cancer, its genetic background, and its origin, in this case, mesenchymal cells." (PMID 39334946, 2024). "The human homolog of PLCδ4 has not been widely characterized, but it could be associated with pathologies and cellular mechanisms like those described for other PLC isoforms, such as cancer development and neurodegenerative diseases." (PMID 39334946, 2024).
tumor (1 paper, 2024). "All in all, we hypothesize that PLCδ4 could represent a sort of tumor suppressor, given that its forced expression slows growth and reduces sensitivity to vincristine." (PMID 39334946, 2024).
PLCD4 also shares sentences with these, for which no sentence is quoted: autoimmune thyroid disease (1 paper); female sterility (1); hypercortisolemia (1); liposarcoma (1); multinodular goiter (1); osteosarcoma (1); rhabdomyosarcoma (1).